ENSG00000271949 (novel transcript, LRRC8C-LRRC8D readthrough)
Gene: Protein-coding gene on chromosome 1 (89,633,140 to 89,933,250, forward strand). Ensembl gene ENSG00000271949.
Genetic constraint (gnomAD): Missense variants: 38 observed, 61.08 expected, observed/expected ratio (o/e) 0.62, 90% interval 0.48 to 0.81. Synonymous variants: 22 observed, 23.74 expected, observed/expected ratio (o/e) 0.93, 90% interval 0.66 to 1.32.